MARCHF1 (membrane associated ring-CH-type finger 1)
Description:
E3 ubiquitin-protein ligase that mediates ubiquitination of TFRC, CD86, FAS and MHC class II proteins, such as HLA-DR alpha and beta, and promotes their subsequent endocytosis and sorting to lysosomes via multivesicular bodies. By constitutively ubiquitinating MHC class II proteins in immature dendritic cells, down-regulates their cell surface localization thus sequestering them in the intracellular endosomal system. Also regulates insulin sensitivity by controlling surface expression of the insulin receptor subunit beta/INSR by direct ubiquitination and degradation. (Microbial infection) Plays a role in iron metabolism by regulating the levels of the transferrin receptor TFRC during human cytomegalovirus infection, subsequently contributing to a proviral effect.
Synonyms: MARCH-I; MARCH1; RNF171; FLJ20668
Tractability: Antibody: UniProt places it where antibodies can reach, with high confidence; its Gene Ontology location is reachable by antibodies, with high confidence; UniProt predicts a signal peptide or a membrane-spanning region. PROTAC: UniProt records ubiquitination sites on it.
Gene: Protein-coding gene on chromosome 4 (163,524,298 to 164,384,050, reverse strand). Ensembl gene ENSG00000145416.
Subcellular location: Golgi apparatus, trans-Golgi network membrane; Lysosome membrane; Cytoplasmic vesicle membrane; Late endosome membrane; Early endosome membrane; Cell membrane
Subcellular location (Human Protein Atlas): Vesicles; Endoplasmic reticulum; Golgi apparatus
Gene Ontology:
Molecular function: MHC protein binding; ubiquitin protein ligase activity; zinc ion binding
Biological process: antigen processing and presentation of peptide antigen via MHC class II; immune response; protein polyubiquitination; protein ubiquitination
Cellular component: early endosome membrane; endosome; late endosome membrane; lysosomal membrane; lysosome; plasma membrane; cytoplasm; endoplasmic reticulum membrane; trans-Golgi network membrane; cytoplasmic vesicle membrane; Golgi apparatus
Genetic constraint (gnomAD): Loss-of-function variants: 34 observed, 52.19 expected, observed/expected ratio (o/e) 0.65, 90% interval 0.5 to 0.87. The upper end of that interval is the gene's LOEUF score, 0.87, which puts it in group 3 of 6, group 1 being the genes least tolerant of losing a copy. Missense variants: 564 observed, 662.63 expected, observed/expected ratio (o/e) 0.85, 90% interval 0.79 to 0.91. Synonymous variants: 227 observed, 237.69 expected, observed/expected ratio (o/e) 0.96, 90% interval 0.86 to 1.07.
Homologues: Orthologues: chimpanzee MARCHF1 (99% identical), macaque MARCHF1 (87% identical), dog MARCHF1 (83% identical), mouse Marchf1 (80% identical), rat Marchf1 (80% identical), rabbit MARCHF1 (75% identical), pig MARCHF1 (69% identical), guinea pig MARCHF1 (51% identical), zebrafish marchf1 (42% identical), tropical clawed frog marchf1 (37% identical). Paralogues in human: MARCHF8 (43% identical), MARCHF4 (14% identical), MARCHF9 (13% identical), MARCHF11 (13% identical), MARCHF2 (11% identical), MARCHF3 (11% identical).
Diseases named in the same sentence as MARCHF1 in open-access papers:
MARCHF1 is named in the same sentence as 61 diseases in open-access papers, as found by Europe PMC text mining. Sharing a sentence is not in itself a finding about the gene and the disease. The quoted sentences say what the papers report.
diabetes (2 papers, 2018 to 2022). "Our results suggest that MARCHF1 is associated with a rapid eGFR decline in patients with hypertension and diabetes." (PMID 36422279, 2022). "We found that the rs10009742 in the MARCHF1 gene on chromosome 4q32.3 was associated with a rapid eGFR decline (a decrease of ≥5 mL/min/1.73 m2 per year) in patients with hypertension and diabetes in Korea." (PMID 36422279, 2022). "Excessive ubiquitination caused by genetic variants of rs10009742 in MARCHF1 impairs the activity of cellular insulin by degrading insulin receptor-β on the cell surface, leading to diabetes." (PMID 36422279, 2022). "In conclusion, the MARCHF1 gene on chromosome locus 4q32.3 (rs10009742, reference/effective allele, C/T) was associated with a very rapid decline in eGFR, an indicator of CKD progression, in patients with hypertension and diabetes in Korea." (PMID 36422279, 2022).
chronic kidney disease (1 paper, 2022). Impairment of the renal function secondary to chronic kidney damage persisting for three or more months. "Furthermore, MARCHF1 affects the pimelylcarnitine metabolite concentration, which may mediate chronic kidney disease progression by inducing oxidative stress in the endoplasmic reticulum." (PMID 36422279, 2022).
epilepsy (1 paper, 2024). A brain disorder characterized by episodes of abnormally increased neuronal discharge resulting in transient episodes of sensory or motor neurological dysfunction, or psychic dysfunction. "Based on the literature and database searches, there is association with seizures or epilepsy for five of the brain expressed genes (Marchf1, Tma16, Npy1r, Npy5r, Psd3)." (PMID 38862622, 2024).
renal dysplasia (1 paper, 2022). Renal dysplasia is a form of renal malformation in which the kidney(s) are present but their development is abnormal and incomplete. "The MARCHF1 gene has been associated with fatty acids (FAs), glucose metabolism, and renal dysplasia." (PMID 36422279, 2022).
renal fibrosis (1 paper, 2022). A final common manifestation of a wide variety of chronic kidney diseases characterized by glomerulosclerosis and tubulointerstitial fibrosis. "MARCHF1 ubiquitination modulates tubulo-interstitial inflammation, renal fibrosis, and FAO." (PMID 36422279, 2022).
MARCHF1 also shares sentences with these, for which no sentence is quoted: tumor (15 papers); cancer (12); hepatocellular carcinoma (11); infection (7); ovarian carcinoma (7); bladder cancer (6); HIV-1 infection (4); breast carcinoma (3); liver cancer (3); lung adenocarcinoma (3); lung squamous cell carcinoma (3); asthma (2); colon adenocarcinoma (2); colorectal cancer (2); glioma (2); immune disorder (2); Insulin resistance (2); Obesity (2); oral squamous cell carcinoma (2); prostate adenocarcinoma (2); rectum adenocarcinoma (2); skin cutaneous melanoma (2); type 2 diabetes (2); acute myeloid leukemia (1); airway allergy (1); airway hyperresponsiveness (1); allergic asthma (1); Allergy (1); atherosclerosis (1); Cerebral ischemia (1).
A further 26 diseases each share a sentence with MARCHF1 in 1 paper.